OR6C70 (olfactory receptor family 6 subfamily C member 70)
Description:
Odorant receptor.
Tractability: Antibody: UniProt places it where antibodies can reach, with medium confidence; UniProt predicts a signal peptide or a membrane-spanning region; its Gene Ontology location is reachable by antibodies, with medium confidence.
Gene: Protein-coding gene on chromosome 12 (55,469,200 to 55,470,138, reverse strand). Ensembl gene ENSG00000184954.
Subcellular location: Cell membrane
Pathways (Reactome):
Sensory Perception: Expression and translocation of olfactory receptors
Gene Ontology:
Molecular function: olfactory receptor activity; G protein-coupled receptor activity
Biological process: detection of chemical stimulus involved in sensory perception of smell; G protein-coupled receptor signaling pathway
Cellular component: plasma membrane; membrane
Genetic constraint (gnomAD): Missense variants: 422 observed, 359.73 expected, observed/expected ratio (o/e) 1.17, 90% interval 1.08 to 1.27. Synonymous variants: 152 observed, 133.84 expected, observed/expected ratio (o/e) 1.14, 90% interval 1 to 1.3.
Homologues: Orthologues: rat Olr1057 (82% identical), rabbit OR6C70 (81% identical), rat Or6c70 (81% identical), mouse Or6c70 (80% identical), mouse Or6c217 (79% identical). Paralogues in human: OR6C6 (73% identical), OR6C75 (71% identical), OR6C76 (70% identical), OR6C3 (67% identical), OR6C65 (67% identical), OR6C74 (66% identical), OR6C1 (65% identical), OR6C2 (64% identical), OR6C4 (64% identical), OR2AP1 (63% identical), OR6C68 (61% identical), OR6T1 (46% identical), and 6 more.